AFP (alpha fetoprotein)
Diseases named in the same sentence as AFP in open-access papers (continued):
Sharing a sentence is not in itself a finding about the gene and the disease.
liver cancer (continued). "Serum MIF, GP73, PIVKA-II, AFP-L3 and AFP all have certain diagnostic value for primary liver cancer; the combined detection of five serological tumor markers can significantly improve the sensitivity, specificity and accuracy of the diagnosis of primary liver cancer, with higher diagnostic value." (PMID 34475930, 2021). "However, other physiological factors often interfere with the detection of AFP, and its accuracy is insufficient to correctly reflect the risk of liver cancer." (PMID 34771525, 2021). "Notably, the expression of EFNA4 in 90 tissue samples of liver cancer was related to the expression of alpha-fetoprotein (AFP; χ2 test, p = 0.0362) and the risk of vascular invasion (χ2 test, p = 0.0319)." (PMID 34484860, 2021). "At present, serum AFP is the preferred diagnostic marker for primary liver cancer." (PMID 32536814, 2020). "To further confirm that the miPS-Huh7cmP1 cells were enriched with the cells expressing liver cancer-associated markers (AFP, GPC3 and CK19) and CSC markers (CD44, CD133 and CD24), we examined the gene expression levels compared to those in miPSCs and miPS-Huh7cm cells." (PMID 32203212, 2020). "In addition, high AFP expression was associated with the molecular classification of liver cancer, including iCluster (Chi-square: 16.86, P = 0.0002)." (PMID 31897235, 2020). "De-methylation of cytosine from CpG di-nucleotides in AFP promoter may be the cause of AFP re-expression in adult human liver cancer tissue." (PMID 31897235, 2020). "Early diagnosis of liver cancer depends on biomarker sensitivity and specificity.Serum biomarkers such as AFP are used to diagnose liver cancer in high-risk patientswith minimal invasiveness and rapid response.Combined use of biomarkers for early detection of liver cancer is prevalent." (PMID 33585001, 2020). "An elevated level of a protein in the blood can result from its increased secretion from the diseased tissue (e.g., alpha-fetoprotein in liver cancer) or it can be caused by the inflammation associated with cancer (e.g., increased production of serum amyloid A in lung cancer patients)." (PMID 32575471, 2020). "Therefore, many research efforts have been made to search for the pathogenic genes and diagnostic markers of liver cancer, such as the tumor size, alpha fetoprotein level and various differentially-expressed genes in primary liver cancer tissues." (PMID 31966062, 2020). "Identifying such proteins might provide new ways to treat YAP-associated liver cancer and highlight potential biomarkers to increase the sensitivity of AFP, CD166 and MCAM to diagnose liver cancer." (PMID 31501420, 2019). "Elevated levels of serum total triglyceride and cholesterol are associated with liver function disorder; elevated activities of both AST and ALT indicate liver injury; and elevated activity of γ-GT and the level of AFP are associated with increased liver cancer risk." (PMID 31443426, 2019). "Interestingly, the same group of genes was strongly up-regulated in cancer nodules together with classical liver cancer markers (Afp, encoding alpha-fetoprotein among many others)." (PMID 29734330, 2018). "Serum AFP was first introduced as diagnostic marker for primary liver cancer in 1964." (PMID 28657540, 2017). "Documents evidenced that metastasis of cancer cells maybe occurred concomitant with carcinogenesis 22, implicated that expression of AFP in early stage of hepatocarcinogenesis involved in malignant behaviours of liver cancer cells." (PMID 26756858, 2016). "It is thus possible that people at higher risk of liver cancer may be deterred from taking regular AFP and CEA tests on account of travelling, missing the window of early detection and treatment." (PMID 26610504, 2015). "Elevated levels of serum alpha-fetoprotein (AFP) indicate a high risk of liver cancer." (PMID 26099202, 2015).
liver cancer (continued). "Additionally, the reduction in AFP levels may correspond with a decreased risk of metastasis, as lower AFP levels have been associated with better prognoses and lower metastatic potential in liver cancer." (PMID 40573279, 2025). "This indicated that demographic information and certain laboratory tests (TBIL, ALB and PLT) could improve the diagnostic efficacy for liver cancers and highlighted the significance of the combined detection of serum AFP, AFP-L3% and PIVKA-II in the diagnosis of liver cancers." (PMID 40708828, 2025). "A large-scale, multicenter clinical trial data showed that plasma Hsp90α could be used as an early diagnostic marker in the diagnosis of patients with liver cancer, and its diagnostic performance was better than that of AFP (sensitivity 92.7% and specificity 91.3%)." (PMID 34348726, 2021). "The α-fetoprotein (AFP) and soluble intercellular adhesion molecule-1 (sICAM-1) have certain diagnostic value, but their potential value in prognosis prediction, especially immunotherapy response prediction, remains unclear in liver cancer." (PMID 34696675, 2021). "Multivariate analysis revealed that younger age, normal alpha fetoprotein, single site of extrahepatic disease, local treatment to the primary tumor, and surgery to the metastatic disease were associated with better overall survival and liver cancer-specific survival." (PMID 32723336, 2020). "In addition, miR-18a was significantly elevated in human HCC compared to non-tumor liver, was negatively correlated with GCLC expression in human HCC, and was positively correlated with alpha-fetoprotein (AFP) expression, which is associated with aggressive liver cancer." (PMID 28443280, 2017). "Independent prognostic factors identified by Cox regression included age, alpha-fetoprotein, gamma-glutamyl transpeptidase, and the Barcelona Clinic Liver Cancer stage." (PMID 42111212, 2026). "Subgroup analyses will be performed based on PD-L1 expression, etiology, Barcelona Clinic Liver Cancer stage, alpha-fetoprotein concentration, macrovascular invasion, and extrahepatic spread." (PMID 41988192, 2026). "The representative species of these two enterotypes effectively predicted viral load, immune cells, HBeAg, and the liver cancer marker AFP." (PMID 41244669, 2025). "Currently, alpha-fetoprotein (AFP) remains the most utilized serum biomarker in liver cancer, playing a critical role in its screening, diagnosis, and prognostic assessment." (PMID 39829957, 2025). "We then confirmed that liver cancer organoids expressed liver cancer-specific characteristics by checking the expression of liver cancer differentiation markers (AFP and KRT19), proliferation marker (Ki67), and EMT activation markers (PDGFRB and α-SMA)." (PMID 40852642, 2025). "Previous research has demonstrated that miR-1236-3p directly targets the 3′ untranslated region (UTR) of AFP in liver cancer, leading to its downregulation." (PMID 40429981, 2025). "A significant number of liver cancer cases show increased levels of alpha-fetoprotein (AFP) in the blood, as this protein is released into the bloodstream." (PMID 40308592, 2025). "Yang and co-workers reported an electrochemical immunosensor utilizing MWCNTs-COOH functionalized with Fe3O4 and AuNPs for the detection of the liver cancer marker alpha-fetoprotein (AFP)." (PMID 40509251, 2025). "Previously, various clinical prediction models, such as GALAD and ASAP, have been employed for liver cancer discrimination and diagnosis, with AFP playing a crucial role despite their excellent performance." (PMID 40161339, 2025). "AFP, a glycoprotein widely utilized in diagnosing and monitoring liver cancer, exhibits a sensitivity of only 60% at the optimal threshold (10–20 ng/mL) for HCC, with limited specificity." (PMID 40161339, 2025).
liver cancer (continued). "Meanwhile, drawing on the successful experience of South Korea in improving the survival rate of liver cancer through systematic early screening (ultrasound combined with AFP monitoring), a hierarchical medical treatment system is constructed." (PMID 41255611, 2025). "Lastly, AFP-CAR T-cells demonstrated strong antitumor efficacy in a well-established intraperitoneal liver cancer xenograft paradigm (n = 6)." (PMID 40098955, 2025). "The immunomodulatory effects of Huaier, combined with its ability to lower tumor markers such as AFP and inhibit metastatic spread, provide a strong rationale for its inclusion in multi-modal treatment strategies for liver cancer." (PMID 40573279, 2025). "The use of protein-based biomarkers, such as tumor antigens and tumor-related proteins, can be exemplified by the use of alpha-fetoprotein (AFP) for treating liver cancer." (PMID 39996991, 2025). "AFP, a glycoprotein belonging to the serum albumin gene family, is commonly utilized as a biomarker for liver cancer." (PMID 41341390, 2025). "In this study, a lateral flow aptasensor was developed for rapid detection of the liver cancer tumor marker alpha-fetoprotein (AFP) with a naked-eye detection limit of 10 ng/mL." (PMID 39942588, 2025). "qPCR analysis revealed that the gene expression of liver cancer-specific differentiation markers AFP and ALB was much higher in patient-derived liver cancer organoids (5-fold and 4-fold, respectively) than in normal liver organoids." (PMID 40852642, 2025). "Recent studies have revealed that AFP plays a multifaceted role in various malignant tumors, including liver cancer." (PMID 40430002, 2025). "Immunostaining for liver cancer differentiation markers (AFP and ALB) and the proliferation marker (Ki67) demonstrated that the orthotopic PDX tumors of the Liver ECM group showed greater progression compared to those of the Matrigel group." (PMID 40852642, 2025). "Oxidative stress also plays an important role in the process of virus-induced liver cancer (HCC), causing a significant increase in the level of 14,15-DiHETrE that was found to be associated with the levels of tumor marker α-fetoprotein (AFP)." (PMID 41163120, 2025). "Antigenicity, molecular weight, subcellular localization and expression site predictions were used to shortlist liver cancer associated proteins including AMBP, CFB, CDHR5, VTN, APOBR, AFP, SERPINA1 and APOE." (PMID 39752339, 2025). "In liver cancer, the tumor marker AFP was of high MI throughout disease progression, but CA19-9 and CA125 became more important toward the end of life." (PMID 39885364, 2025). "The mice that received DEN injections demonstrated significant elevations in serological markers of liver cancer, angiogenesis, and proinflammatory cytokines, including AFP, DCP, VEGF, and TNF-α (All P < 0.001), compared to the negative control group." (PMID 41602133, 2025). "Studies have shown that when AFP levels consistently exceed 400 ng/mL, liver cancer can be highly suspected." (PMID 40458724, 2025). "An AFP concentration exceeding 400 ng/mL is generally considered a reliable diagnostic marker for HCC, making AFP a critical clinical biomarker for liver cancer." (PMID 40277545, 2025). "Specifically, AFP induces macrophage polarization towards the M2 phenotype, a state characterized by a reduced capacity for phagocytosis, which allows liver cancer cells to evade the immune response." (PMID 40430002, 2025). "For liver cancer, two different approaches for detecting alpha-fetoprotein (AFP) illustrate how material choice directly impacts performance." (PMID 41440247, 2025). "These insights provide a basis for future therapeutic strategies aimed at improving liver cancer treatment by modulating macrophage function via AFP." (PMID 40430002, 2025). "AFP, alpha-fetoprotein, is closely related to liver malignant tumors and germ cell tumors to a certain extent, which is of certain value in the diagnosis of ovarian malignant tumors." (PMID 39911631, 2025).
liver cancer (continued). "The cumulative data demonstrate that miR-1236-3p works as a tumor suppressor in the growth, proliferation, invasion and migration of liver cancer by modulating the PTEN/PI3K/Akt route that is mediated by AFP." (PMID 40429981, 2025). "Alpha-fetoprotein (AFP) is widely used to detect liver cancer but has limitations in early-stage HCC detection." (PMID 40332516, 2025). "Still, they specifically degranulated, produced cytokines, and lysed liver cancer cells that were HLA-A*02:01+/AFP+." (PMID 40098955, 2025). "The ABCR scoring system is based on AFP, Barcelona clinic liver cancer, Child-Pugh scores, and response." (PMID 39758864, 2025). "In particular, AFP, a widely used biomarker in liver cancer diagnosis, has a sensitivity of only 62.4% at the diagnostic threshold of 20 ng/mL, rendering it insufficient for early detection and prone to false negatives." (PMID 40060905, 2025). "While alpha-fetoprotein (AFP) is a well-recognized biomarker for liver cancer, its role in gastric cancer (GC) remains less explored." (PMID 40485723, 2025). "The study reported a detection limit of 0.20 μM for AFP, which is significant for early diagnosis and monitoring of liver cancer." (PMID 40509251, 2025). "Cumulative evidence suggests that miR-1236-3p acts as a tumor suppressor in the proliferation, migration, and invasion of liver cancer via modulating the PTEN/PI3K/Akt pathway mediated by AFP." (PMID 40429981, 2025). "AFP has been used as a biomarker for liver cancer; however, it has low sensitivity and specificity, which necessitates the search for other, more accurate biomarkers." (PMID 40322566, 2025). "Nonetheless, given that AFP is known to play a role in liver cancer, germ cell tumors, and other types of tumors, AFP-targeted cancer therapies are emerging as a particularly promising field of research." (PMID 40430002, 2025). "Recent research has found that AFP not only serves as a tumor marker but also promotes liver cancer recurrence by regulating the characteristics of liver cancer stem cells." (PMID 40458724, 2025). "The immune escape effect of AFP is another reason for the high early recurrence rate after liver cancer surgery." (PMID 40458724, 2025). "Alpha-fetoprotein (AFP) is a critical biomarker for liver cancer progression, and its reduction indicates decreased tumor activity." (PMID 40573279, 2025). "Currently, liver cancer diagnosis relies on imaging and biochemical tests, including ultrasound, computed tomography (CT), magnetic resonance imaging (MRI), and alpha-fetoprotein (AFP)." (PMID 41357578, 2025). "Other studies have revealed correlations between PFAS concentrations and altered liver biomarkers such as ALP, AST, and AFP in liver cancer patients." (PMID 40317014, 2025). "Alpha-fetoprotein (AFP) is a well-known biomarker for liver cancer, and its clinical utility is widely recognized." (PMID 40430002, 2025). "Blocking the function of AFP or inhibiting its interaction with TME can disrupt the connection between liver cancer cells and TME, thereby inhibiting tumor growth and diffusion." (PMID 38660138, 2024). "OneTest (20/20 GeneSystems) measures different tumor antigens, such as prostate‐specific antigen, cancer antigen 125, and alpha‐fetoprotein for prostate, ovarian, and liver cancer respectively." (PMID 39463807, 2024). "Early-stage patients exhibiting abnormal clinical symptoms can benefit from laboratory tests, where blood and urine samples are analyzed for markers such as AFP and γ-glutamyl transpeptidase, helping to identify liver cancer in its initial phases." (PMID 39654222, 2024). "Alpha-fetoprotein (AFP) is a specific serum glycoprotein vital for liver cancer diagnosis; however, its sensitivity and specificity are limited." (PMID 38834966, 2024). "Exosomes-based biomarkers of liver cancer were directly compared with traditional biomarkers such as AFP." (PMID 39497820, 2024).
liver cancer (continued). "The development of AFP and ultrasonography screening techniques in 1970 further improved the detection level of liver cancer." (PMID 38756657, 2024). "In TME, sinusoidal endothelial cells become capillarized or defenestrated after exposure to inflammatory factors, such as IL-6 and AFP, which promote liver fibrosis, cirrhosis, and liver cancer." (PMID 38660138, 2024). "In China, the screening criteria also encompass individuals with a family history of liver cancer, and serum AFP is used as an additional screening measure." (PMID 39736748, 2024). "AFP is a key diagnostic and prognostic marker for HCC and serves as an immunotherapeutic target as a tumor-associated antigen in liver cancer." (PMID 38500533, 2024). "Biomarkers such as CA-125, used in ovarian cancer, and AFP, used in liver cancer diagnosis, enable the identification of cancers even in high-risk groups where rapid diagnosis is essential." (PMID 39685591, 2024). "Further elucidation of the mechanisms involved in the interaction between AFP and TAMs and potential intervention strategies can undoubtedly enhance the clinical efficacy of immunotherapy for liver cancer." (PMID 38660138, 2024). "Similar to the need of excluding active hepatitis, pregnancy, and reproductive system tumors when diagnosing liver cancer with AFP, active hepatitis and acute liver damage should also be excluded for IL-41-based liver cancer diagnosis." (PMID 38835390, 2024). "In summary, targeting the AFP-TME interaction in HCC can disrupt the link between liver cancer cells and the TME, inhibiting tumor growth, invasion, and immune evasion." (PMID 38660138, 2024). "The median tumor marker levels at the time of liver cancer diagnosis were AFP = 8 ng/mL (HCC), CA19-9 = 23 U/mL (CCA), and CEA = 31 ng/mL (CRLM)." (PMID 38473290, 2024). "Its expression levels correlate with alpha-fetoprotein (AFP) levels in patients with liver cancer (correlation coefficient 0.36, P value < 0.001)." (PMID 38334941, 2024). "Presently, several new biomarkers, such as AFP, lectin-reactive alpha-fetoprotein, des-gamma-carboxyprothrombin, and Golgi protein 73, have been identified as effective indicators of liver cancer." (PMID 38707500, 2024). "A recent study demonstrated that AFP can affect the function of macrophages in phagocytizing liver cancer cells by inducing the polarization of TAMs." (PMID 38660138, 2024). "The biomarkers for liver cancer are AFP (Alpha fetoprotein) and CEA, and the biomarker for prostate cancer is PSA (Prostate-specific antigen)." (PMID 39091905, 2024). "The diagnostic performance of PTX3 was assessed using ROC curve analysis and compared with the liver cancer tumor markers AFP and CA199." (PMID 39686456, 2024). "Alpha-fetoprotein (AFP) in serum is considered as an important protein biomarker for early-stage diagnosis of liver cancer." (PMID 39194596, 2024). "Simultaneously, several studies have demonstrated that AFP can accelerate liver cancer progression by upregulating LCSC markers K19 and CXCR4." (PMID 38660138, 2024). "Nevertheless, M. nodiflorum displayed the remarked decline in AFP proving the inhibition of AFP synthesis in liver cancer cells." (PMID 39735355, 2024). "Proteins such as PSA (prostate-specific antigen) in prostate cancer, HER2 in breast cancer, CA-125 in ovarian cancer, and AFP (alpha-fetoprotein) in liver cancer are particularly important in cancer diagnosis." (PMID 39685591, 2024). "Presently, routine screening for liver cancer commonly involves abdominal ultrasound and alpha-fetoprotein (AFP) level assessments." (PMID 39432605, 2024). "Studies have found that in the TME, the X protein of HBV can stimulate the expression of reprogramming-related proteins by increasing AFP expression, thus inducing the proliferation of liver cancer stem cells (LCSCs)." (PMID 38660138, 2024). "The team used TBS combined with AFP levels to evaluate prognostic outcomes in cases undergoing radical liver cancer resection." (PMID 39555448, 2024).